INS (insulin)
Diseases named in the same sentence as INS in open-access papers (continued):
Sharing a sentence is not in itself a finding about the gene and the disease.
Insulin resistance (continued). "Changes in BW, blood pressure (BP), BGL, water and food consumption, serum insulin, serum glucagon and insulin resistance (IR) were monitored." (PMID 35265127, 2022). "This challenges the well-accepted notion of the selectivity of hepatic insulin resistance that comprises a blunted acute effect of insulin on gluconeogenesis with a more positive effect of chronic hyperinsulinemia on lipogenesis." (PMID 36009446, 2022). "Insulin resistance is due to an effect on the insulin receptor requiring an increase in insulin dose in patients with type 2 diabetes over time." (PMID 36013252, 2022). "Among them, it has been reported that serine phosphorylation of IRS-1, an insulin resistance indicator induced by insulin-resistant inducers such as JNK and IKKβ, is critical to developing insulin resistance." (PMID 36145191, 2022). "Disturbance of insulin signaling leads to insulin resistance (IR), a condition where cells, primarily within the insulin-sensitive tissues, lose their functional response to insulin." (PMID 36504710, 2022). "Obesity-induced inflammation is also known to impair insulin signaling which contributes to insulin resistance and dyslipidemia and ultimately to the progression of cardiovascular disease (CVD)." (PMID 35782930, 2022). "Regular alcohol consumption can lead to a state of generalized insulin resistance by inhibiting, for example, glucose disposal or insulin release in men17." (PMID 36535973, 2022). "One of the first to indicate a role for galectin-1 in insulin resistance was a study of 10 obese but otherwise healthy insulin-resistant men treated with the insulin sensitizing PPAR-γ agonist rosiglitazone (4 mg bid) for 14 days." (PMID 36295832, 2022). "OSA causes sleep fragmentation and sympathetic adrenal axis excitability, which reduces tissue sensitivity to insulin, insulin secretion, and hepatic glucose breakdown, aggravating insulin resistance." (PMID 35165839, 2022). "The APP/PSEN1 mice appeared resistant to the hypoxia-mediated trend for lower insulin levels and lesser insulin resistance seen in wt." (PMID 35852609, 2022). "In conclusion, R4 RGS members play key roles in insulin secretion and insulin resistance and the related physiological processes." (PMID 36497154, 2022). "The authors reported a highly significant correlation between OBT and abnormal values for insulin levels and the homeostatic model assessment of insulin resistance (HOMA), both being specific features of NASH." (PMID 36552942, 2022). "In response to insulin demand, β cells undergo proliferation as a compensatory defense mechanism against insulin resistance." (PMID 35563490, 2022). "β cell mass in subjects with obesity is assumed to increase, since plasma insulin levels in obese subjects increase to compensate for insulin resistance, a process known as hyperinsulinemia." (PMID 35198097, 2022). "Some patients have a trend of increasing insulin demand in the subsequent clinical treatment, which reflects the rising insulin resistance index (Homa IR)." (PMID 36530444, 2022). "It is worth noting that, although they are easily available, HOMA-IR, HOMA-B, and serum adiponectin levels are indirect markers for insulin resistance and insulin secretion." (PMID 35268464, 2022). "DM is commonly classified into two types: type 1 DM (T1DM), caused by an absolute deficiency of insulin ensuing destruction of pancreatic beta cells, and type 2 DM (T2DM), resulting from insulin resistance and subsequent deficiency of insulin secretion." (PMID 36114541, 2022). "Insulin resistance is a metabolic disorder characterized by the decreased response to insulin in muscle, liver, and adipose cells." (PMID 35737707, 2022). "The resulting data were used to determine indices indicative of pancreatic insulin secretion and muscle and liver insulin resistance." (PMID 35327447, 2022).
Insulin resistance (continued). "The increase in FFAs around insulin-dependent tissue results in insulin resistance which decreases glucose uptake resulting in compensatory hyperinsulinemia, as seen in the DIPD group." (PMID 35898447, 2022). "Certain NPs, most of which have antioxidant properties, have been found to be beneficial in activating the insulin signaling pathway, regulating blood glucose levels, and decreasing insulin resistance in diabetic models." (PMID 35887304, 2022). "When insulin levels are persistently high, cells develop insulin resistance, an early sign of type 2 diabetes." (PMID 35203869, 2022). "The induction of insulin resistance in skeletal muscles is a key phenomenon, and impairments in insulin signaling in this tissue directly contribute to hyperglycemia, which has been confirmed by the following results of insulin signaling pathway experiment." (PMID 35782940, 2022). "It has been reported that 10 nM of TCDD decreases the mRNA level of GLUT4 in 3T3-L1 adipocytes, impairing the insulin signaling pathway and leading to insulin resistance." (PMID 36358481, 2022). "This study also shows that insulin resistance, as measured by the insulin-stimulated Akt phosphorylation response, correlates with age in both the control group and the type 2 diabetes group." (PMID 35884888, 2022). "PCS contributed to insulin resistance: It altered insulin signaling in skeletal muscle through the activation of extracellular signal-regulated kinases." (PMID 35448889, 2022). "It has been proposed that NAFLD contributes to impaired plasma insulin clearance in people with insulin resistance, presumably because NAFLD impairs hepatic functioning." (PMID 35054781, 2022). "Homeostatic model assessment of insulin resistance (HOMA-IR) was calculated as insulin (μIU/ml) × glucose (mg/dl)/405." (PMID 35677718, 2022). "The increased area under the curve for glucose and insulin suggests glucose intolerance alongside insulin resistance as a result of overfeeding." (PMID 35676248, 2022). "Insulin resistance is associated with impairment of the PI3K pathway, while the MAPK pathway often continues to respond to insulin." (PMID 36107629, 2022). "Brain insulin resistance is considered the impairment of insulin activity and aggravates neuronal cell death, leading to memory loss and cognitive impairment." (PMID 35328405, 2022). "Obesity activates the NF-κB pathway and increases the expressions of proinflammatory cytokines such as TNF-α and interleukin-6 (IL-6) in adipose tissue, thereby disrupting insulin signaling and triggering insulin resistance and NAFLD." (PMID 36305727, 2022). "This insulin-impaired sensitivity promotes an increased secretion of insulin, creating a vicious cycle since a hyperinsulinemia status leads to more insulin resistance." (PMID 36233611, 2022). "Oral glucose tolerance test and insulin tolerance test determined the impact of eugenol on HFD/STZ-induced insulin resistance." (PMID 36424928, 2022). "To ensure that this improvement in insulin sensitivity was due to the activation of α7nAchR, we investigated the effect of α7nAchR expression on neuronal insulin resistance." (PMID 35883638, 2022). "Other studies have found that increased serum insulin levels and insulin resistance are directly related to cognitive impairment." (PMID 36498726, 2022). "Small but significant improvements were detected in risk factors such as body weight, waist circumference, fat mass, BMI, blood pressure, total cholesterol, triglycerides, fasting blood glucose, fasting insulin, and insulin resistance." (PMID 35276815, 2022). "In insulin resistance, insulin receptor tyrosine kinase activity is reduced, and insulin and IGF‐1 binding to the receptor is reduced, resulting in insufficient signal transduction pathways." (PMID 36105371, 2022). "The demand for insulin remains high, due to persistent hyperglycaemia coupled with insulin resistance, and a decline in β cell function and β cell numbers ensues." (PMID 35986507, 2022).
Insulin resistance (continued). "For example, long-term insulin injections will produce insulin resistance (IR) and decrease the body’s endogenous insulin production, enhancing the patient’s dependence on insulin." (PMID 36479195, 2022). "Hoga1 ASO treatment ameliorated the clinical indexes of insulin resistance including glucose, insulin, and homeostatic model assessment of insulin resistance (HOMA-IR) levels in HFD-induced mice." (PMID 36035184, 2022). "In the present study, the levels of insulin, insulin resistance, and visceral fat mass were decreased, and HDL-cholesterol was increased via FEO inhalation." (PMID 35215391, 2022). "Assessments of glucose parameters and indexes for insulin resistance indicated that FD pigs showed higher levels of fructosamine (p < 0.005) and a trend toward higher insulin levels (p = 0.09) and HOMA-β index (p = 0.05)." (PMID 36290436, 2022). "In the prediabetic state, the insulin resistance induced hyperinsulinemia can be compensated by increased rates of insulin biosynthesis until the compensatory mechanisms ultimately collapse along with a gradually decreasing insulin synthesizing capacity." (PMID 35416515, 2022). "We found significant (p < 0.05) increases in serum levels of PCSK9, serum insulin, insulin resistance, and leptin at the end of Ramadan compared with pre-fasting levels." (PMID 35454343, 2022). "The mechanism for improved menstrual cycle during MET treatment is related to decreased insulin resistance including a direct effect on ovarian insulin sensitivity." (PMID 36557221, 2022). "T2DM is a metabolic disease caused by a complex combination of environmental and genetic factors, characterized by impaired insulin secretion and insulin resistance." (PMID 36051387, 2022). "Herbal medicines act via different mechanisms aiming at reducing insulin resistance, increasing insulin secretion, protecting pancreatic beta cells, and thereby lowering circulating blood glucose levels." (PMID 35807526, 2022). "We observe no improved glucose tolerance in older male mice or in high fat diet-fed mice, corroborating the prediction that global insulin resistance obscures the effects of β-cell specific insulin resistance." (PMID 35136059, 2022). "Insulin resistance and impaired insulin secretion, which are characteristics of T2D, can be modeled in animals by using different diets, such as high-sucrose, high-fat, or cafeteria (high-fat and high-sucrose) diets, or by direct genetic disruption." (PMID 36297523, 2022). "Dysregulation of SPARC alters the levels of inflammatory cytokines related to insulin-stimulated glucose transport, glucose transporter 4, and ATP synthesis in mitochondria, and eventually induces insulin resistance." (PMID 34751020, 2022). "Mice fed an HFD logically exhibited insulin resistance, but insulin levels during OGTT and at the end of the experiment were unchanged after CCE supplementation compared with HFD." (PMID 35448490, 2022). "This will further exacerbate insulin resistance and contribute to decreased insulin-mediated glucose uptake and disposal in muscles." (PMID 35897752, 2022). "Experimental studies document that MGO contributes to the pathogenesis of insulin resistance via a modification of insulin structure and function, modulation of insulin secretion, and insulin signaling." (PMID 36432614, 2022). "For this reason, insulin resistance, which consists in a lower insulin activity at the cellular level accompanied by an impaired metabolism of carbohydrates, lipids, and proteins, can have a crucial impact on cognitive functions." (PMID 35600880, 2022). "Insulin resistance in hepatocytes compromises the inhibitory effect of insulin on follistatin and thus disrupts the ratio of glucagon-to-insulin, which controls follistatin synthesis." (PMID 35053214, 2022).
Insulin resistance (continued). "Alternatively, during the development of insulin resistance, insulin cannot inhibit the production of glucose in the liver but paradoxically accelerates the synthesis of lipids, leading to an increase in triglycerides and blood glucose." (PMID 36498726, 2022). "We have previously shown that in the microvasculature of healthy subjects, insulin enhances capillary perfusion and that insulin resistance can block that response and even provoke a reduced perfusion response to insulin." (PMID 34894721, 2022). "Currently in research, an array of metrics and indices that rely on glucose concentrations at a single time point or as a simple function of glucose and insulin are regularly employed to quantify glucose tolerance or insulin resistance independently." (PMID 36281448, 2022). "Insulin resistance consequentially raises insulin level and prevents insulin suppression of fat lipolysis leading to peripheral lipid deposition, lipotoxicity and activated pro-oxidant/inflammatory pathways with non-adipose organs as key victims." (PMID 35881588, 2022). "Anethum graveolens significantly reduced fasting insulin (as insulin sensitizer; −2 mIU/L; −3 to −1), insulin resistance (−0.9; −1.8 to −0.1), and LDL-C (−10 mg/dl; −19 to −2)." (PMID 35754481, 2022). "Pathogenic expansion of the VAT is related to insulin resistance, inflammation, and dyslipidemia, while the expansion of SAT is frequently associated with the improvement of metabolic status and insulin sensitivity." (PMID 36012206, 2022). "Among the several functions of NO, Pieper concluded that NO alterations play a major part in developing insulin resistance and T2D by showing its capability to modulate peripheral and hepatic glucose metabolism and insulin production." (PMID 35627115, 2022). "Insulin resistance enhances the hepatic glucose production and diminishes glucose uptake in insulin-sensitive cells, including adipose tissue, skeletal muscle and liver tissue." (PMID 36093068, 2022). "This led us to conclude that metabolic syndrome was characterized by both macro and microvascular insulin resistance due, at least in part, to a diminished nitric oxide-mediated vasodilatory action of insulin." (PMID 34957859, 2022). "The dysregulation of adipocytecytokines not only leads to a decrease in insulin-mediated glucose uptake byinfluencing insulin signaling pathway, but also increases ectopic lipidaccumulation, which eventually aggravates insulin resistance and T2DM." (PMID 35976267, 2022). "T2DM is a chronic disease characterized by high levels of glucose in the blood, impaired insulin secretion and/or insulin resistance due to dysregulated carbohydrate, lipid and protein metabolism." (PMID 35039631, 2022). "Insulin resistance defines an impairment in the biologic response to insulin action in target tissues, primarily the liver, muscle, adipose tissue, and brain." (PMID 35204710, 2022). "People with IGT have moderate to severe muscle insulin resistance; therefore, skeletal muscle reduces the uptake and utilization of glucose under the action of insulin." (PMID 35712028, 2022). "Peripheral insulin resistance is accompanied by central manifestations like defective insulin signaling, neuroinflammation, brain abnormalities, as well as cognitive and memory deficits." (PMID 36374861, 2022). "Especially in male subjects, however, the measured insulin levels showed signs of insulin resistance (IR) in one-fifth of the subjects." (PMID 36447164, 2022). "It has been reported that these adipokines are the key mediators of insulin resistance because they suppress insulin activity (especially TNF-α)." (PMID 35320949, 2022). "Separately, dysfunctional insulin secretion and insulin resistance as well as elevated serum leptin levels have been reported in patients with NAFLD44." (PMID 36075960, 2022).
Insulin resistance (continued). "Insulin resistance is one of the key causative factors of NAFLD, and iron accumulation in the body can also interfere with the function of Islet β Cells, affecting insulin synthesis and secretion, and resulting in insulin resistance." (PMID 36330148, 2022). "Homeostatic Model Assessment of insulin resistance is a method that uses baseline (fasting) glucose and insulin or C-peptide concentrations to determine IR." (PMID 35964948, 2022). "Maternal obesity and an energy-dense diet can cause an increase in insulin and IGF-1 serum levels, producing metabolic disorders, such as insulin resistance, GDM, and high birth weight (> 4,000 g) due to a higher level of body fat." (PMID 35813659, 2022). "These two outcomes combined indicated that insulin resistance and insulin levels are positively correlated with circulating levels of irisin under the condition of metabolic disorders but that the correlation is not obvious in metabolic healthy individuals." (PMID 36271416, 2022). "We considered fasting serum insulin levels to be a reasonable “Sharrett equivalent” (i.e., the basis for comparison), as compensatory hyperinsulinemia is the defining characteristic of insulin resistance." (PMID 36079745, 2022). "T1DM is caused by absolute lack of insulin whereas T2DM is mainly due to ineffective insulin action often referred to as insulin resistance due to defective insulin secretion or irresponsiveness on the part of insulin receptors." (PMID 35723349, 2022). "In our experiment, the fasting blood glucose concentration and fasting insulin content of rats in each group were incorporated into the HOMA-IR formula to calculate the insulin resistance index." (PMID 35811955, 2022). "On the other hand, hyperuricemia induces insulin resistance through suppression of both basal and glucose-stimulated insulin secretion, induction of β-cell dysfunction through NF-κB signaling pathway, reduction of serum nitric oxide levels and bioavailability." (PMID 36514085, 2022). "Surprisingly, the increased plasma insulin and insulin resistance index HOMA-IR were reversed by the RPE extract to the normal levels in diabetic mice." (PMID 35741945, 2022). "BCAA play a central role in insulin resistance and appear detrimental to insulin sensitivity in animals and humans." (PMID 35774538, 2022). "A third limitation is the use of HOMA-IR to characterize individuals as insulin sensitive or insulin resistance." (PMID 35045086, 2022). "The role of muscle and the pancreas in impaired glucose uptake and decreasing insulin production leads to insulin resistance, resulting in the development of hyperinsulinemia that ultimately leads to MeS." (PMID 35268685, 2022). "Several studies in transgenic mouse models have shown that the inhibition of Pik3r1 enhances PI3K activity and improves insulin signaling and glucose homeostasis in high fat diet fed obese mice and mice with genetically induced insulin resistance." (PMID 36287121, 2022). "Adiponectin not only affects cancer cells by directly inhibiting proliferation and invasion, but also indirectly, by reducing insulin resistance and insulin levels." (PMID 35164764, 2022). "Administration of STZ was found capable of developing peripheral insulin resistance or impairing insulin secretion from pancreatic β cells and it is sufficient to induce noninsulin-dependent diabetes mellitus (type 2) in animals." (PMID 35620596, 2022). "Further analysis revealed that a few mice failed to maintain normoglycemia and that some of the mice became less responsive to exogenous insulin injections indicating the re-establishment of insulin resistance." (PMID 35563490, 2022). "The most common method used in practice is measuring the HOMA-IR indicator (homeostasis model of assessment of insulin resistance), calculated on the basis of fasting insulin and glucose concentrations." (PMID 36613051, 2022).